CPO (carboxypeptidase O)
Description:
Carboxypeptidase which preferentially cleaves C-terminal acidic residues from peptides and proteins. Can also cleave C-terminal hydrophobic amino acids, with a preference for small residues over large residues.
Tractability: Antibody: UniProt places it where antibodies can reach, with high confidence; its Gene Ontology location is reachable by antibodies, with high confidence; UniProt predicts a signal peptide or a membrane-spanning region.
Gene: Protein-coding gene on chromosome 2 (206,939,518 to 206,969,474, forward strand). Ensembl gene ENSG00000144410.
Subcellular location: Apical cell membrane
Gene Ontology:
Molecular function: metallocarboxypeptidase activity; zinc ion binding
Biological process: proteolysis
Cellular component: apical plasma membrane; plasma membrane
Genetic constraint (gnomAD): Loss-of-function variants: 8 observed, 8.69 expected, observed/expected ratio (o/e) 0.92, 90% interval 0.54 to 1.62. That is too few expected variants to judge how well the gene tolerates losing a copy. Missense variants: 186 observed, 211.99 expected, observed/expected ratio (o/e) 0.88, 90% interval 0.78 to 0.99. Synonymous variants: 93 observed, 84.39 expected, observed/expected ratio (o/e) 1.1, 90% interval 0.93 to 1.31.
Homologues: Orthologues: chimpanzee CPO (99% identical), macaque CPO (98% identical), pig CPO (84% identical), dog CPO (83% identical), rabbit CPO (80% identical), tropical clawed frog cpo (55% identical), tropical clawed frog cpo.2 (51% identical), zebrafish cpo (46% identical), Caenorhabditis elegans Y47G6A.19 (34% identical), Drosophila melanogaster CG18585 (34% identical), Drosophila melanogaster CG3097 (34% identical), Caenorhabditis elegans T06A4.1 (33% identical), and 17 more. Paralogues in human: CPB1 (40% identical), CPA6 (40% identical), CPA3 (40% identical), CPB2 (39% identical), CPA4 (34% identical), CPA1 (34% identical), CPA2 (34% identical), CPA5 (30% identical).
Diseases named in the same sentence as CPO in open-access papers:
CPO is named in the same sentence as 9 diseases in open-access papers, as found by Europe PMC text mining. Sharing a sentence is not in itself a finding about the gene and the disease. The quoted sentences say what the papers report.
Anxiety (1 paper, 2023). Intense feelings of nervousness, tension, or panic often arise in response to interpersonal stresses. "This test also revealed that CPO-treated rats spent significantly less time in the center of the arena compared to vehicle-treated rats, suggesting increased anxiety in these animals." (PMID 35137321, 2023). "Therefore, taken all together, our findings support the notion that perinatal exposure to CPO reproduce behavioral alterations typical of neurodevelopmental disorders, including altered social behavior, impaired learning and memory, increased anxiety, and delayed motor development." (PMID 35137321, 2023).
choledocholithiasis (1 paper, 2019). Presence or formation of gallstones in the common bile duct. "Therefore, through the data obtained, it can be concluded that it is safe to indicate both CPO and MRCP in cases suspected of choledocholithiasis through the initial clinical, laboratory and ultrasound, since the two methods are concordant in their results." (PMID 30624525, 2019).
colon cancer (1 paper, 2022). "CPO was observed to be downregulated in our current analysis and no report on its downregulation in either colon cancer or CRC was found in the literature." (PMID 36293321, 2022).
nephritis (1 paper, 2016). Inflammation of renal tissue. "The top 5 up-regulated genes based upon fold change between groups were: carbamoyl-phosphate synthase 1 (CPS1), carboxypeptidase O (CPO), tubulointerstitial nephritis antigen (TINAG), solute carrier family 7, member 9 (SLC7A9), and solute carrier family 6, member 19 (SLC6A19)." (PMID 27093613, 2016).
orofacial cleft (1 paper, 2024). A disorder of facial skeleton that is characterized by cleft lip and/or cleft palate that result in feeding, speech and hearing problems caused by failures during development. "The other types of orofacial clefts were characterized by a low (CBT, CP-FRI or CP-FLI, CSPo-FI, and CRT or CLT + CP-FRI or CP-FLI) or null (CPo-FC, CPo-FI, CP-FRC or CP-FLC, DG-G, and CP-FRI or CP-FLI + CPo-FI) frequency of staphylococcal oral colonization." (PMID 39338954, 2024).
infection (3 papers, 2010 to 2024). The state of being infected such as from the introduction of a foreign agent such as serum, vaccine, antigenic substance or organism. "Infection of these cells with baculovirus encoding Xenopus CPO paralogs resulted in expression of all four paralogs, as detected by western blot, both in the cell lysates and in the conditioned medium." (PMID 36781897, 2023). "With mock infection (without CPO treatment) in C6/36 cells, the cell death rates were 2.15% and 2.12%, respectively; the rates did not evidently change even when cells were treated with CPO (1.14% and 9.85%, respectively)." (PMID 20819232, 2010).
CPO also shares sentences with these, for which no sentence is quoted: breast carcinoma (1 paper); cognitive decline (1); neurodevelopmental disorder (1).